CCL20 (C-C motif chemokine ligand 20)
Diseases named in the same sentence as CCL20 in open-access papers (continued):
Sharing a sentence is not in itself a finding about the gene and the disease.
infection (continued). "Moreover, we indicated nDens of 2 genes induced and 2 genes repressed in all infection performed and nDens of all genes discussed above (IL-1β, IL-6, IL-12, TNF-α, IL-10, ADAM19, CCR7, CCL20 and IL-18)." (PMID 21436989, 2011). "L. major induced only a small increase in CCL4 and CCL5 mRNA at the site of infection, while infection did not induce CCL20 mRNA (data not shown)." (PMID 20140197, 2010). "In order to elucidate the pathways that are involved in the regulated expression of the antimicrobial peptide genes, lysozyme, CCL20 and SLPI, LA-4 cells were pre-incubated with specific inhibitors of NF-κB and p38 MAPK pathways (BAY11-7082 and SB203580 respectively) prior to the infection process." (PMID 19806192, 2009). "CCL20, also known as MIP-3α, is a far less potent recruiter of neutrophils, instead displaying a stronger preference for lymphocytes and dendritic cells, helping develop adaptive immune responses at the site of infection as opposed to just innate immunity." (PMID 41081505, 2025). "Infections with pso variants (especially with the HK2 variant lacking O-Ag biosynthesis) activated endothelial cells with abundant expression of cell adhesion molecules (ICAM-1 and VCAM-1) and inflammatory mediators (CCL2, CXCL1, CXCL8, CCL20, and IL-6)." (PMID 40570043, 2025). "Finally, results showed a decrease of the CCL20 gene expression at the peak of infection but no longer during the resolution." (PMID 38756777, 2024). "Notably, CXCL8 and CCL20 are induced early during vaginal SIV infection in macaques followed by secondary inflammatory process likely driven by CCL5 and other CK-producing cells, leading to recruitment of immune cells and fueling infection." (PMID 35051209, 2022). "UDP-mediated activation of P2Y6 receptor promotes the recruitment of inflammatory cells to sites of inflammation or infection by inducing the production of various chemokines including CCL2 (monocyte chemotactic protein 1, MCP-1), CXCL8 (IL-8) and CCL20 (macrophage inflammatory protein-3α, MIP-3α)." (PMID 34064383, 2021). "Notably, the abundance of seven chemokines, such as C–C motif chemokine ligand 14 (CCL14), CCL20, CCL25, CCL5, C–X–C motif chemokine ligand 10 (CXCL10), CXCL14, and atypical chemokine receptor 3 (ACKR3), was significantly higher by infection in the R line of the TSF flock." (PMID 30678719, 2019). "Expression of an array of cytokines (CSF3 [G-CSF], IFNγ, IL-1β, IL-6, IL-22, IL-17A, and IL-10), chemokines (CCL20, CXCL2 and CXCL9) and receptors (CD40) known to be involved in the regulation of S. pneumoniae inflammatory response was measured at 0, 6, 24, and 48 h post-infection." (PMID 30333823, 2018). "CC chemokines including CCL2 and CCL20 were significantly induced upon HRV72 infection suggesting that non-neutrophilic immune response could be potentially provoked by this virus." (PMID 28558071, 2017). "The significant increase in colonic CCL20 expression in mice treated with GW9662 during infection combined with flow data displaying significantly higher percentages of DC and T cells in the colonic lamina propria further supports an enhanced active recruitment of these cells early during infection." (PMID 23469071, 2013). "The expression of 277 genes was induced >2-fold in a statistically significant manner by infection with Mtb:Δ-sigH at the 0 hr time-point Some of the genes with the greatest induction included CCL4 (17.6-fold), CXCL2 (10-fold), CCL7 (6.5-fold) and CCL20 (4.3-fold)." (PMID 22235255, 2012). "In our study, BVDV-2 infected goat PBMCs showed increased transcription of CCL3, CCL4, CCL5, CCL20, CXCL10 and decrease of CCL2, suggesting that such chemokines may contribute to the recruitment and regulation of macrophages or other inflammatory cells to the infected sites after infection." (PMID 31226933, 2019). "Unlike the IL-19 and CCL20 mRNA expression profiles, PEDV only increased IL-8 gene expression at an early time point post-infection." (PMID 36142545, 2022).
infection (continued). "While we could not find any description of CCL20 induction by GC specifically, there is evidence that production of this chemokine can be induced by bacterial products and is suppressed by estrogen, which together would explain its particularly potent induction in diestrus infection." (PMID 30134832, 2018). "Conversely, there was no significant increase in mRNA expression of CCL5, CCL19, CCL20 and CCL21 chemokines after infection in both MyD88+/+ and MyD88−/− mice." (PMID 23374751, 2013). "A reduction was noted during infection with both TTSS mutant strains, with no strains modulating CCL20 production at this time." (PMID 22046438, 2011). "The B cell chemoattractant, CXCL13 was dramatically lower in aged as compared to juvenile animals, regardless of infection status whereas CXCL12 and CCL20, known dendritic cell (DC) chemoattractants, were much higher in mock and SARS-CoV infected aged animals (unpaired student T-test)." (PMID 24642138, 2014).
bacterial infection (17 papers, 2009 to 2025). "Lung epithelial cell derived CCL20 has been shown to be critical for neutrophil recruitment during bacterial infection." (PMID 38907250, 2024). "The upregulated genes included genes encoding innate immunity effectors, such as IL-17C, CCL20, and TNF, which contribute to combat bacterial infections." (PMID 26485688, 2015). "The mechanism for this synergistic effect on CCL20 expression is unknown but we could hypothesise that it may be partly due to the increase in bacterial adhesion in the presence of simvastatin, as CCL20 expression in bacterial infections is linked to this phenotype." (PMID 25010049, 2014). "CCL20 has recently also been shown to be produced in response to other bacterial infections." (PMID 24699535, 2014). "Further functional data on the recruitment of neutrophils by CCL20 and CCR6 during acute bacterial infections are sparse." (PMID 24699535, 2014). "Although CCL20 is produced by astrocytes in response to bacterial infections and EAE, to the best of our knowledge, ours is the first report to demonstrate neuronal expression of CCL20." (PMID 22040257, 2011). "There have been no studies on the role of CCL20 and CCR6 in bacterial infections of the central nervous system." (PMID 24699535, 2014).
inflammation (10 papers, 2014 to 2025). Aberrant reaction of the microcirculation characterized by movement of fluid and leukocytes from the blood into extravascular tissues. "CCL20 is an inflammatory mediator whose expression was detectable during renal inflammation in an experimental murine model; thus, cTFH cells may migrate toward the CCL20 gradient." (PMID 36293075, 2022). "CCL20 plays an important role in the pathogenesis of liver inflammation and fibrosis in NASH." (PMID 32418112, 2020). "In the current study, we newly clarified the possible effects of S1P/S1PR3 axis on the expression of the CCL20 from the airway ECs and showed therapeutic effect of VPC23019 on airway eosinophilic inflammation." (PMID 30192865, 2018).
infectious disease (4 papers, 2017 to 2025). A disorder directly resulting from the presence and activity of a microbial, viral, or parasitic agent in humans. "CCL20 levels critically influence immune cell migration and activation, thereby significantly impacting inflammatory responses, infectious diseases, and oncogenesis." (PMID 39228662, 2024).
kidney disease (4 papers, 2022 to 2025). "We therefore hypothesised that CCL20 levels in biological fluids could be associated with kidney disease outcomes." (PMID 41226600, 2025). "Among microRNAs (miRNAs), miR-143-5p downregulates CCL20 expression, and this is therapeutically relevant for kidney disease." (PMID 41226600, 2025). "In humans, increased expression of the IL-8, CCL4, and CCL20 genes are involved in the pathogenesis of renal diseases." (PMID 37268977, 2023). "CCL20 has also been found to be increased in kidney disease." (PMID 38643262, 2024). "We next assessed plasma CCL20 in ADPKD, a primary kidney disease that is not immunologically mediated." (PMID 41226600, 2025).
colorectal (2 papers, 2023 to 2024). "This decrease of CCL20, IL-8 and PPARG gene expression and the high proliferation status of primary colorectal tumourspheres after oxaliplatin treatment strongly correlate with a metastatic phenotype, as we observed in our TNMplot data for normal, tumorous, and metastatic tissues." (PMID 36835258, 2023).
gastrointestinal disease (2 papers, 2021 to 2025). A disease that occurs in the gastrointestinal system, excluding the hepatobiliary system. "CCL20 has been associated with disease severity and mucosal inflammation in gastrointestinal diseases and autoimmune disorders." (PMID 40277930, 2025). "Besides, the disease susceptibility prediction found that aberrant expressed CCL5 and CCL20 were mainly related to gastrointestinal disease, endocrine system disease, and the disease of cell proliferation disorder (including LIHC)." (PMID 34938730, 2021).
heart diseases (2 papers, 2017 to 2022). "Thus, CCL20-induction by stimulation with TNF-α may be a good marker associated with heart diseases." (PMID 36012347, 2022). "Taken together, these studies support the hypothesis that CCL20-neutralising antibodies administered to patients with ischaemic heart disease have the potential to suppress the migration of CCR6+ IL-17A-producing γδT cells and improve prognosis." (PMID 28798316, 2017).
immune dysfunction (2 papers, 2017 to 2022). "Thus, the macrophage-mediated CCL20/CCR6 axis is involved in the pathogenesis of EMs by promoting the proliferation and migration of ESCs as well as being closely related to immune dysfunction." (PMID 35841069, 2022).
neurological diseases (2 papers, 2021 to 2025). "Studies in astrocytes revealed PERK-mediated activation of JAK-STAT3 signaling and induction of cytokines including CCL20 as a potential mechanism underlying neurological diseases." (PMID 34725321, 2021).
respiratory disease (2 papers, 2017 to 2022). "Therefore, the strongly correlated IFNγ and CCL20 may mark a circulating readout of severe respiratory disease complications." (PMID 34957382, 2022).
benign tumors (1 paper, 2022). "We found that CCL20 levels could differentiate between benign tumors and OC with 60.61% sensitivity and 75.44% specificity at the optimal cutoff value of 38.79 pg/ml." (PMID 36387204, 2022).
hematological malignancies (1 paper, 2024). "Of particular interest is the new T cell therapy for solid tumors, similar to the Car-T in hematological malignancies, which could be used in small dysplastic lesions of the larynx, especially when CCL20 and CCR4 are the most important gene alterations observed in dysplasia." (PMID 39273632, 2024).
intestinal diseases (1 paper, 2025). "In summary, our MR analysis has provided genetic evidence supporting the causal effects of multiple inflammatory factors – such as CCL19, CD40L, CCL20, PD-L1, IL-5, and M-CSF – on 5 distinct intestinal diseases (IBD, UC, CD, CAC, and CRC)." (PMID 41239614, 2025).
psychiatric disorder (1 paper, 2022). A disorder characterized by behavioral and/or psychological abnormalities, often accompanied by physical symptoms. "A previous study showed that CCL20 of the dorsolateral prefrontal cortex were significantly decreased in suicide completers (some of them accompanied with comorbid psychiatric disorder) compared to control (individuals died for other reasons besides suicide)." (PMID 35618730, 2022).
vasculopathy (1 paper, 2021). "Based on these backgrounds, we investigated the potential role of CCL20/CCR6 in SSc vasculopathy and the contribution of FLI1 deficiency to this process by a series of experiments with clinical samples, cultured endothelial cells, and animal models." (PMID 34774095, 2021). "With respect to CCL20, we have recently found that serum CCL20 levels correlate with mean pulmonary arterial pressure (mPAP) in SSc patients, suggesting that the CCL20/CCR6 axis underlies the developmental mechanism of SSc vasculopathy." (PMID 34774095, 2021). "Taken together with our recent data regarding the association of the CCL20/CCR6 axis with SSc-PAH, we hypothesized that FLI1 deficiency regulates the CCL20/CCR6 axis in the context of SSc vasculopathy." (PMID 34774095, 2021). "This study was undertaken to investigate the role of the CCL20/CCR6 axis in the development of SSc vasculopathy because serum CCL20 levels correlate with mPAP values in SSc patients." (PMID 34774095, 2021). "Considering a proangiogenic effect of CCL20 on endothelial cells via CCR6, the CCL20/CCR6 axis may contribute to the development of SSc vasculopathy." (PMID 34774095, 2021). "Taken together with evidence that the CCL20/CCR6 axis functions as a potent pro-angiogenic regulator, CCR6 upregulation may be involved in the development of SSc vasculopathy." (PMID 34774095, 2021). "Taken together, these results suggest that CCL20 secreted from dermal fibroblasts plays a role in the early stage of dcSSc (disease duration of < 2 years), while CCR6 up-regulation in endothelial cells contributes to the development of SSc vasculopathy throughout the whole disease course." (PMID 34774095, 2021).
CCL20 also shares sentences with these, for which no sentence is quoted: malaria (7 papers); adenocarcinoma (6); bipolar disorder (4); pancreatic ductal adenocarcinoma (4); autoimmune hepatitis (3); bacterial vaginosis (3); dermatitis (3); esophageal squamous cell carcinoma (3); multiple myeloma (3); pancreatic adenocarcinoma (3); psoriatic arthritis (3); AIDS (2); alopecia (2); Anxiety (2); cholangiocarcinoma (2); colorectal adenoma (2); diabetic retinopathy (2); fungal infection (2); intra-amniotic infection (2); malignant neoplasm of thyroid gland (2); metabolic disorders (2); metastatic melanoma (2); monocytic leukemia (2); neurodegenerative disease (2); osteoarthritis (2); papillary carcinoma of the thyroid (2); pneumonia (2); polymyositis (2); rectal adenocarcinoma (2); schwannoma (2).
A further 121 diseases each share a sentence with CCL20 in 2 papers or fewer.